MIR18B (microRNA 18b)
Synonyms: hsa-mir-18b; MIRN18B; mir-18b
Gene: MicroRNA gene on chromosome X (134,170,041 to 134,170,111, reverse strand). Ensembl gene ENSG00000283931.
Gene Ontology:
Biological process: miRNA-mediated post-transcriptional gene silencing
Cellular component: RISC complex